ALB (albumin)
Diseases named in the same sentence as ALB in open-access papers (continued):
Sharing a sentence is not in itself a finding about the gene and the disease.
tumor (continued). "The increased cytokine concentration is a hallmark of cancer cachexia accelerating tumor-associated tissue wasting and anorexia and thus, decreases in albumin concentration may well reflect cancer cachexia." (PMID 27863481, 2016). "While photosensitizers can reach the lesion more easily, and thus selectively accumulate in tumor tissues, molecular association with albumin may be performed in physiological solutions, thus conferring biocompatible characteristics to the formulation." (PMID 24341795, 2013). "Thus, our observations may support that TM4SF5-expressing HCC cells can utilize extracellular ALB via macropinocytosis for ATP-linked respiration and cell migration, possibly leading to intrahepatic metastasis involving tumor nodule expansion or multifocality." (PMID 40186033, 2025). "In clinical practice, neutrophil percentage and albumin are easily accessible, inexpensive, and convenient to measure, and the calculation of their ratio is also very intuitive and convenient, which can provide a quick risk assessment reference for long-term follow-up of tumor patients." (PMID 40313883, 2025). "Oxygen free radical production by the tumor microenvironment additionally causes increased albumin oxidation/glycation in peripheral spaces, thus leading to reduced antioxidant capacity and greater albumin breakdown either through hepatic endocytosis or direct tumor cell absorption." (PMID 40103850, 2025). "Association with albumin may therefore improve tumor bioavailability of siRNA." (PMID 38383524, 2024). "Furthermore, it was hypothesized that the lowered albumin level in tumor patients is caused by weight loss, particularly cellular weight loss." (PMID 36297021, 2022). "In terms of changes in other laboratory indicators, whether in accordance with the different tumor locations or the different risk grades for subgroup analysis, the albumin, prealbumin, and total protein of all patients at discharge were lower than those at admission (all p < 0.05)." (PMID 35187038, 2022). "Besides IL-6 and IL-8 values, baseline albumin value ≥ 17 g/L (p = 0.008) and tumor diameter ≥ 65 mm (p = 0.021) were associated with overall survival, whereas there was a trend for better survival in patients with total bilirubin < 17 g/L (p = 0.058) and portal vein invasion (p = 0.099)." (PMID 33855585, 2022). "Recently, the expression of caveolin-1, an important protein related to endocytosis and overexpressed in tumor cells, was associated with albumin–PTX sensitivity in in vitro models, suggesting that this protein might participate in the cell uptake of nanoparticles." (PMID 36015347, 2022). "Moreover, many cytokines from systemic inflammatory response related to tumor progression may inhibit the albumin synthesis, and accelerate the albumin loss to interstitial space." (PMID 34445989, 2021). "has shown that a preoperative low ALB level in patients with BC resulted in an increased risk of overall and cancer-specific death, compared with patients with a normal ALB level, and that the decreased serum ALB level may be a risk factor for poor tumor prognosis." (PMID 33959511, 2021). "Interestingly, the combination of Cremophor EL and dehydrated ethanol has been shown to inhibit the binding of Paclitaxel to albumin, suggesting that these solvents may hinder albumin-associated transport of Paclitaxel to the tumor microenvironment." (PMID 34336673, 2021). "Each 1 g/dL drop in albumin was associated with a 2.4 times higher risk of hospitalization (95% CI 1.2–5.0, P = 0.01) as well as increased number of hospitalizations (coefficient 1.5, 95% CI 0.9–1.5, P = 0.11) after adjusting for other baseline patient, tumor, and treatment related variables." (PMID 32306924, 2020).
tumor (continued). "Upon intravenous injection, Evans blue binds to albumin in the bloodstream and only crosses into the brain through compromised tumor-associated vasculature, thus allowing us to uniquely examine transport of this molecule from the tumor into surrounding parenchyma, similar to Gd." (PMID 30456343, 2018). "Therefore, when an OLA-derivatized drug dissociates from the nanoparticle carrier, its subsequent association with albumin and lipoproteins may influence biodistribution, and enhance its circulation half-life and tumour accumulation." (PMID 27071376, 2016). "Consequently, several laboratories are developing various albumin-based systems for the delivery of a variety of therapeutic and diagnostic compounds to tumours, including chemotherapeutic drugs, nanomedicines, cytokines, nucleic acids, radionuclides, fluorescent molecules, and many others." (PMID 25188308, 2014). "Furthermore, MDR1, MRP, and LRP expression wasn’t associated with tumor stage, response to first-line therapy, the erythrocyte sedimentation rate, or C reactive protein, beta 2 microglobulin, serum lactate dehydrogenase, and albumin levels." (PMID 24744642, 2012). "Six features were utilized, including age, tumor mutational burden (TMB), blood albumin level, neutrophil–lymphocyte ratio." (PMID 41491583, 2026). "Albumin@MnB achieves potent tumor suppression at reduced boron doses, demonstrating superior efficacy compared with BPA." (PMID 41743161, 2026). "For each albumin platform, a fluorescent dye (Flamma Fluors 648) was introduced in equal amounts and injected into 4T1 tumor-bearing mice." (PMID 41355949, 2026). "Our findings demonstrate that the encapsulation of dBET6 within albumin nanoparticles coated with exosomes can significantly enhance the anti-tumor efficacy of dBET6, potentially addressing the therapeutic challenges associated with TNBC." (PMID 41525248, 2026). "Integrating these advances with our present glycosylation-based approach strengthens the rationale for albumin as a modular nanoplatform that can be rationally engineered to interrogate and therapeutically exploit the tumor microenvironment." (PMID 41355949, 2026). "In parallel, albumin-based nanoparticles have gained prominence as biocompatible carriers capable of improving drug solubility, circulation time, and tumor penetration." (PMID 41489768, 2026). "Overall, albumin-based nanocarriers offer biocompatible, scalable, and tumor-targeted solutions for delivering molecular and genetic therapeutics in TNBC." (PMID 41489768, 2026). "Among them, albumin (Alb)-based NPs offer distinct advantages, including high biocompatibility, efficient drug loading capacity, inherent tumor-targeting potential, and facile surface modification." (PMID 41551982, 2026). "Key markers included C-reactive protein, albumin, neutrophil and lymphocyte counts, creatinine, bilirubin, international normalized ratio, tumor size and number, alpha-fetoprotein, platelet count, and CD4+/CD8+ T-cell levels." (PMID 41869666, 2026). "To overcome DFX's poor solubility and bioavailability, we engineered tumor-targeting, glutathione-responsive albumin nanoparticles modified with cRGD peptides (RGDAB@DFX NPs)." (PMID 41940349, 2026). "The patient subsequently underwent neoadjuvant therapy comprising albumin-bound paclitaxel, camrelizumab, oxaliplatin, and S-1.After four cycles, the tumor significantly reduced in size, with restaging at yT2N2M0 (Stage IIb)." (PMID 41695334, 2026). "This study evaluated the prognostic value of a PET-derived SUVmax/albumin ratio integrating tumor metabolism and nutritional status in patients treated with neoadjuvant FLOT." (PMID 42195217, 2026). "Nanotechnology, particularly albumin-based nanoplatforms, provides an opportunity to overcome these limitations by enhancing solubility, circulation time, and tumor-specific accumulation." (PMID 41489768, 2026).
tumor (continued). "The capacity to aggregate around tumors through transcytosis via specific receptors offers a considerable tumor targeting advantage for albumin-based nanoformulations." (PMID 41598285, 2026). "Albumin is a promising vehicle for anticancer drug delivery due to its high plasma concentration, long half-life and known tumor accumulation." (PMID 41575354, 2026). "Albumin interacts with cellular receptors such as gp60, and penetration occurs through endothelial cells with the help of transcytosis, which promotes deep tumor diffusion." (PMID 41489768, 2026). "After four cycles of neoadjuvant therapy with carboplatin, albumin-bound paclitaxel and pembrolizumab, the tumor lesion regressed markedly." (PMID 42063707, 2026). "Prognostic factors included: N stage, tumor length, chemotherapy cycles, platelet-to-albumin ratio, lymphocyte-to-monocyte ratio, age, body mass index, radiotherapy dose, and neutrophil to monocyte to lymphocyte ratio." (PMID 41480963, 2026). "Independent prognostic factors for poor overall survival included albumin-bilirubin grade 2-3, alpha-fetoprotein ≥400 ng/mL, maximum tumor size ≥8 cm, presence of extrahepatic metastasis, and absence of conversion surgery." (PMID 42112317, 2026). "In conclusion, albumin-based nanocarriers combine biocompatibility, functional versatility, and intrinsic tumor-targeting features to address key limitations in conventional TNBC therapy." (PMID 41489768, 2026). "One of them includes surface modification of albumin nanoparticles via the use of tumor-homing peptides to selectively target TNBC cells." (PMID 41489768, 2026). "Previous studies have shown that albumin regulates the inflammatory response and plays an antioxidant role in tumor development." (PMID 41522516, 2026). "This convergence of pharmacokinetics, natural tumor affinity, and clinical application underscores the pivotal role of albumin in advancing drug delivery and oncology treatment paradigms." (PMID 41489768, 2026). "Gp60 facilitates transcytosis of albumin across the endothelium, while SPARC binds and retains albumin within the tumor microenvironment, increasing the specificity of its cellular uptake and drug delivery." (PMID 41489768, 2026). "SPARC is particularly overexpressed in the tumor microenvironment of TNBC, potentially facilitating the accumulation of albumin-bound therapeutics within both tumor cells and stromal components." (PMID 41489768, 2026). "SPCs in patients will produce a large number of inflammatory factors, further reducing serum albumin and lymphocyte levels, thus inhibiting the anti-tumour effect." (PMID 39673205, 2025). "Albumin-bound sirolimus is a novel mTOR inhibitor that improves drug delivery efficiency and tumor targeting via an albumin carrier." (PMID 40989692, 2025). "Here, we present the case of a patient with a tumor at the gastroesophageal junction who underwent treatment with sintilimab, paclitaxel (albumin-bound), and cisplatin." (PMID 40821850, 2025). "The results of the multivariate analysis indicated that several independent predictive factors were significantly associated with PFS, including ALB, AFP, tumor number, NLR, and PD-1 inhibitor treatment (HR=0.63; 95% CI: 0.46-0.86, P =0.004)." (PMID 40574845, 2025). "Beyond its role in hepatic cell differentiation and regulation of key markers such as ALB and AFP, HNF4α is also important in attenuating cancer‐associated characteristics and suppressing tumor progression." (PMID 41244070, 2025). "Albumin‐bound paclitaxel is a combination of traditional paclitaxel and albumin nanoparticles that bind to cysteine‐rich acidic secretory proteins in the tumor and matrix, thereby enhancing the selective delivery of paclitaxel in PDAC." (PMID 41036616, 2025). "Reduced albumin expression correlates with aggressive tumor behavior, potentially through downregulating metastasis-associated genes such as urokinase plasminogen activator surface receptor (uPAR) and matrix metalloproteinase (MMP)." (PMID 40941632, 2025).
tumor (continued). "Albumin-coated MnO2 nanoparticles can relieve hypoxia in the tumor microenvironment to overcome radiotherapy resistance." (PMID 40777019, 2025). "Low ALB levels cannot effectively remove free radicals, which exacerbates tumor cells proliferation and progression." (PMID 41256327, 2025). "The second most abundant fraction of total protein after albumin is gamma globulins (19.2%), which include, among others, antiviral and tumor-specific antibodies." (PMID 40426873, 2025). "Binding to albumin is important for increasing drug concentration at the tumor target and improving their in vivo therapeutic efficacy, that is why albumin can stand as a promising biomaterial for chemotherapeutic drug delivery." (PMID 40051558, 2025). "Trispecific T-cell–activating constructs (TriTACs) have three domains, binding to a tumor antigen, human serum albumin, and CD3ε." (PMID 40416957, 2025). "Prostate-specific membrane antigen (PSMA) probes conjugated with ALB not only enhance stability in circulation but also improve tumor accumulation, providing robust support for early PCa diagnosis, treatment monitoring, and targeted therapy." (PMID 41030951, 2025). "For instance, aldoxorubicin (a hydrazone derivative tumor-targeted doxorubicin conjugate) binds covalently to albumin, allowing improved drug delivery and retention in tumor tissues." (PMID 40626872, 2025). "This principle is clinically exemplified by Abraxane®, an albumin-nanoparticle formulation of paclitaxel that enhances the drug’s solubility and tumor accumulation while eliminating the need for toxic excipients." (PMID 41154612, 2025). "Liver- and tumor-associated markers, such as AADAC, CLRN3, GPC3, CD40, and ALB, were downregulated in LC4 cells compared to freshly isolated tumor core cells and parental tissues." (PMID 40431665, 2025). "In the univariate analysis, the following variables were identified as significant predictors of PFS: NLR (p = 0.01), PLR (p = 0.011), MLR (p = 0.001), SII (p = 0.008), PIV (p < 0.001), CRP (p = 0.021), albumin (p = 0.021), and tumor size (p = 0.004)." (PMID 39851955, 2025). "Serum albumin, a component of the GNRI, reflects not only nutritional status but also chronic inflammation and immune dysfunction, both of which are implicated in tumor aggressiveness and treatment resistance." (PMID 40710183, 2025). "Thus, TM4SF5-promoted ALB uptake and catabolism were linked to ATP-linked respiration, supporting efficient cellular migration, which presumably allowed intrahepatic metastasis or achievement of multifocality during tumor nodule expansion or formation and cancer progression in the liver." (PMID 40186033, 2025). "In conclusion, the strategy of combining a STING activator and oxaliplatin within an albumin-targeted platinum(iv) complex showed notable tumor-inhibitory activity with distinctly reduced adverse effects." (PMID 40191696, 2025). "TNCC was within the normal reference range for all dogs with neoplasia, and TP was higher than normal in three of the cases, suggesting albumin‐cytologic dissociation." (PMID 40859633, 2025). "The nanoscale size and excellent biocompatibility of albumin-bound paclitaxel facilitate rapid uptake by both tumor and immune cells." (PMID 41550955, 2025). "The study demonstrated a strong association between baseline PIV score and tumor diameter, as well as CEA levels, while showing an inverse relationship with albumin levels." (PMID 40704775, 2025). "In the univariate analysis, age ≥ 75 years, tumor size ≥ 35 mm, albumin level ≤ 3.5 g/dL, neutrophil-to-lymphocyte ratio ≥ 3.5, CA19-9 level ≥ 250 U/mL, and DUPAN-2 level ≥ 750 U/mL were significant prognostic factors." (PMID 39847284, 2025). "Conversely, patients who died due to the tumor had significantly lower values of albumin, hemoglobin, lymphocytes, PNI, and Hb-RDW." (PMID 40323571, 2025).
tumor (continued). "Based on the results of the multivariate analysis, two scoring models were developed using one factor (albumin level or LDH) related to clinical or tumor status and another factor (LMR) related to immune status." (PMID 40579886, 2025). "After sequential treatment with albumin-bound paclitaxel plus cisplatin combined with zimberelimab, both patients achieved marked tumor volume reduction and subsequently underwent reduced-volume BT." (PMID 41346603, 2025). "Decreased albumin levels can impair immune function, leading to a weaker response to cancer cells and promoting tumor growth." (PMID 40650392, 2025). "Low-dose chemotherapy (e.g., albumin-bound paclitaxel) decreases immune-suppressive cell infiltration (such as regulatory T cells), promoting tumor antigen release and dendritic cell maturation, thereby improving the efficacy of PD-1 monoclonal antibodies." (PMID 40862835, 2025). "In line with our findings in HCCA, recent studies in other tumor types have demonstrated that the LDH-to-albumin ratio (LAR) is a significant prognostic biomarker." (PMID 41255598, 2025). "Evidence confirms the prognostic value of serum ALB levels in patients with HCC: lower ALB levels are correlated with larger HCC tumours, whereas elevated levels inhibit tumour growth, invasion, and migration 19-22." (PMID 39781529, 2025). "Partially biomimetic approaches leverage overexpressed receptors, essential nutrient mimicry (e.g., albumin), tumor-homing peptides, and tumor-penetrating peptides to enhance deep tumor targeting." (PMID 40717985, 2025). "In the training set, LASSO regression selected the following 11 variables associated with OS: Age, body mass index (BMI), sex, T stage, N stage, lymphocyte count, neutrophil count, CA19–9 level, clinical stage, tumor size, and serum albumin." (PMID 41208979, 2025). "Recent studies demonstrated heptamethine cyanine dyes (e.g., MHI-148) interact with serum albumin, contributing to tumor uptake and cancer cell internalization." (PMID 39904854, 2025). "The selected characteristics included BMI, albumin, gamma-glutamyl transferase, high-density lipoprotein, tumor echo, envelope, necrosis in tumor, AP enhancement pattern, quick entry in AP, PVP and DP enhanced level, KP degree of washout." (PMID 40746604, 2025). "Specifically, the two groups exhibited comparable age distributions, medical histories, and pre-operative biochemical markers, including vitamin D and albumin levels, as well as tumor markers such as CA 19-9 and CEA." (PMID 40507666, 2025). "Results have showed a higher uptake of 124I-αGal1 in the tumours treated with albumin nanoparticle than in control at 24 and 72 h." (PMID 40507367, 2025). "IS-[111In]In-DO2A-ALB1 markedly increased tumor uptake and decreased renal uptake compared with a control radioligand without ALB, demonstrating the effectiveness of a strategy to introduce ALB into CA-IX-targeted radioligands." (PMID 40308720, 2025). "In this study, to enhance the bioavailability of shikonin and take advantage of tumor cells’ high sugar uptake, we loaded shikonin into albumin nanoparticles coated with dextran." (PMID 41272362, 2025). "This has been done by treating tumour-bearing mice with albumin-bound paclitaxel, which can upregulate Gal1 expression." (PMID 40507367, 2025). "Potentially, drugs can be synthesized as nanoparticles in conjugation with albumin, thus allowing more efficient delivery to the tumor site and prolonged blood circulation." (PMID 40051558, 2025). "There is increasing evidence that inflammatory response and nutritional status play an important role in tumor progression.Serum albumin itself is a major indicator of nutritional status and an inflammation-related predictor." (PMID 40165889, 2025).